MIR30B (microRNA 30b)
Synonyms: hsa-mir-30b; MIRN30B; mir-30b
Gene: MicroRNA gene on chromosome 8 (134,800,520 to 134,800,607, reverse strand). Ensembl gene ENSG00000207582.
Gene Ontology:
Biological process: miRNA-mediated post-transcriptional gene silencing
Cellular component: RISC complex
Homologues: Orthologues: chimpanzee ptr-mir-30b (100% identical), macaque mml-mir-30b (100% identical), guinea pig MIR30B (93% identical), mouse Mir30b (90% identical), pig ssc-mir-30b (85% identical), dog MIR30B (67% identical), zebrafish dre-mir-30b (62% identical), zebrafish dre-mir-30c (55% identical). Paralogues in human: MIR30C1 (66% identical), MIR30C2 (50% identical), MIR30D (40% identical), MIR30E (39% identical), MIR30A (32% identical).
Diseases named in the same sentence as MIR30B in open-access papers:
MIR30B is named in the same sentence as 3 diseases in open-access papers, as found by Europe PMC text mining. Sharing a sentence is not in itself a finding about the gene and the disease. The quoted sentences say what the papers report.
breast carcinoma (1 paper, 2022). "ZFPM2-AS1 (8q22.3) and Mir30B (8q24.22) are implicated in both HCC and breast cancer." (PMID 35632628, 2022).
lung adenocarcinoma (1 paper, 2025). A carcinoma that arises from the lung and is characterized by the presence of malignant glandular epithelial cells. "Many of the identified CNAs also included well-known cancer-related miRNA genes, including MIR92B (ch1q21), MIR30B (ch8q24), and MIR30D (ch8q24), whose frequent amplifications in lung adenocarcinoma have been reported previously, and many others that have not been reported previously." (PMID 40867048, 2025).
MIR30B also shares sentences with these, for which no sentence is quoted: cancer (2 papers).